INS (insulin)
Diseases named in the same sentence as INS in open-access papers (continued):
Sharing a sentence is not in itself a finding about the gene and the disease.
Insulin resistance (continued). "Additionally, the expanding adipose tissue directly produces MCP-1, which not on contributes to the establishment of systemic insulin resistance by undermining insulin signaling at Akt phosphorylation and ERK activation but is also associated with increased adipose inflammation." (PMID 40002337, 2025). "Furthermore, hepatic metabolic dysfunction upregulates ALT activity, sustaining inappropriate gluconeogenesis; in this state, insulin fails to suppress hepatic gluconeogenesis effectively, exacerbating insulin resistance and inducing hyperglycemia and hyperinsulinemia." (PMID 40584102, 2025). "However, the breadth of insulin resistance is highly variable, and there may only be altered glucose metabolism within certain tissues rather than generalized impairment of all insulin signaling." (PMID 40013621, 2025). "Moreover, studies using an insulin-resistant gestational diabetes model demonstrated that β-carotene elevates sex hormone binding globulin (SHBG) expression, which subsequently enhances GLUT4 expression, leading to improved glucose uptake and reduced insulin resistance." (PMID 41515170, 2025). "Importantly, while skeletal muscle accounts for approximately 80% of insulin-stimulated glucose disposal, and is the primary site of insulin resistance in type 2 diabetes, none of the current pharmacotherapies specifically target skeletal muscle to enhance glucose disposal." (PMID 40156616, 2025). "Notably, akin to the sole previous CLA trial involving children, this investigation revealed no significant alterations in fasting glucose, insulin levels, or insulin resistance, suggesting that CLA exerted no adverse effects on these metabolic parameters within this cohort." (PMID 40697709, 2025). "Existing literature proposes that Yerba Maté polyphenols could potentially modulate hepatic insulin signaling by suppressing TNF-α, and may interact with the PI3K-AKT pathway, involving elements like Akt2 and Irs1, possibly contributing to improved peripheral insulin resistance." (PMID 41244043, 2025). "Furthermore, HOMA-IR primarily reflects hepatic insulin resistance and may not capture peripheral insulin sensitivity as comprehensively." (PMID 41458544, 2025). "Notably, the observed metabolic heterogeneity, characterized by impaired insulin secretion rather than classic insulin resistance and the nuanced relationship between BMI and lipid profiles, highlights the need for individualized risk assessment beyond conventional markers." (PMID 41375645, 2025). "Therefore, increasing insulin levels may not always lower BG levels in DN and insulin resistance patients." (PMID 40182806, 2025). "Although our study did not include direct measurements of insulin levels or androgen profiles, the genotype–phenotype correlation is biologically plausible, supported by extensive literature linking INSR gene variants to insulin resistance and hyperandrogenic symptoms." (PMID 40725495, 2025). "In addition, improvements in insulin resistance were more accurately reflected by triglyceride-based indices (such as METS-IR and TyG) rather than traditional insulin-dependent markers (like HOMA-IR or QUICKI), underscoring the limitations of relying solely on fasting insulin levels." (PMID 40565353, 2025). "In the case of systemic insulin resistance, until pancreatic beta-cell activity no longer adequately meets the augmented insulin demand, extra glucose stays in the bloodstream due to decreased insulin-stimulated glucose transport/use and the cells suffer a hypoglycemic state (prediabetes)." (PMID 40277891, 2025). "Insulin resistance is a metabolic disorder in which glucose uptake by various tissues (e.g., skeletal muscles, liver, and adipose tissue) is less effective, regardless of normal or even elevated insulin levels in the blood, since insulin’s main role is to promote this process." (PMID 41473651, 2025).
Insulin resistance (continued). "Additionally, the research conducted on a rat model of insulin resistance induced by a high-fat and high-sucrose diet indicated that CBG (30 mg/kg) could improve liver insulin sensitivity by heightening the phosphorylation of Akt and lessening the phosphorylation of GSK-3B." (PMID 40643519, 2025). "Thus, while proximal insulin signaling defects may be a contributing factor, they are unlikely to be the primary drivers of insulin resistance." (PMID 40806697, 2025). "Interestingly, neuronal androgen signaling might contribute toward driving peripheral insulin resistance in PCOS, since kisspeptin neuron-specific AR knockout improves whole-body insulin-stimulated glucose disposal (and other PCOS-like traits) in a letrozole-induced mouse model of PCOS." (PMID 40013621, 2025). "Furthermore, studies suggest that BCKA, rather than BCAA, is the key mediator of cardiac insulin resistance and could serve as a target for modifying cardiac insulin sensitivity." (PMID 40036545, 2025). "Compared to traditional surrogate indices for insulin resistance, the TyG-BMI index offers the advantages of being readily available and cost-effective, as it does not require additional measurements such as C-peptide or insulin levels, thereby reducing the financial burden on patients." (PMID 41541195, 2025). "However, the addition of metformin to insulin for 6 months did not improve insulin resistance." (PMID 41285865, 2025). "Consequently, elevated insulin concentrations may not necessarily reduce BG concentrations in patients with DN and insulin resistance." (PMID 40182806, 2025). "However, it has not yet been established whether reducing total daily insulin dose may lead to a reduction in insulin resistance in type 1 diabetes." (PMID 41285865, 2025). "Therefore, we propose the presence of a cumulative risk effect, whereby our participants' progression to T2D may primarily stem from decreased insulin secretion as the GRS increases, compounded by the exacerbating factor of higher VFA contributing to increased insulin resistance." (PMID 39902403, 2025). "Additionally, insulin resistance was not assessed, as fasting insulin levels were not measured." (PMID 41026958, 2025). "In conclusion, the greater insulin requirement and ICU LOS in SGLT2i DKA compared to non-SGLT2i DKA may be explained by the greater prevalence of precipitating intercurrent illnesses in SGLT2i DKA and by the greater insulin resistance in T2D, which constituted the majority of cases of SGLT2i DKA." (PMID 40843859, 2025). "However, the expression of IRS-2 was not restored by myocardin upregulation, and serum insulin levels suggested that myocardin upregulation may not alter systemic insulin resistance." (PMID 38505620, 2024). "Although a link between ectopic lipid accumulation and insulin resistance is accepted, the favoured hypothesis is that, rather than triglyceride itself, lipid intermediates such as diacylglycerol (DAG) and ceramide are suggested to be involved in insulin resistance." (PMID 38356104, 2024). "A possible explanation for why the considerable reduction in lipolysis did not result in improved insulin sensitivity could be that lactate as an alternative energy substrate may intrinsically induce insulin resistance, similar to the concept of the “glucose-fatty acid cycle”." (PMID 38324259, 2024). "Finally, HOMA2-IR may not reflect long-term levels of insulin resistance when calculated from a single measurement of plasma glucose and insulin concentrations." (PMID 38388407, 2024). "Moreover, in the HFD + STZ group, the AUC value of the insulin tolerance test (ITT) was found to be remarkably augmented by 6.2-fold higher than in healthy animals (33,687.0 ± 1705.7 mg/dL/min vs. 5469.0 ± 267.6, respectively), indicating insulin resistance (IR)." (PMID 38673735, 2024).
Insulin resistance (continued). "This hypothesis was tested by characterizing different chemerin forms by specific ELISA in the plasma of 18 participants with T2D and 116 without T2D who also had their insulin resistance measured by steady-state plasma glucose (SSPG) concentration during an insulin suppression test." (PMID 38672278, 2024). "As particular indices of IR are considered as markers of different disorders, the obtained results may indicate the differences in beta-cell function (AUC (ins/glu)) and peripheral insulin sensitivity (Matsuda index), while not in hepatic insulin resistance (HOMA)." (PMID 39125447, 2024). "Exercise may improve IR by regulating different molecular mechanisms such as mitochondrial function and autophagy Among all the strategies to treat insulin resistance, a non-pharmacological approach with exercise is a simple, cost-effective measure to improve insulin sensitivity." (PMID 39518747, 2024). "Additionally, while no significant changes were observed in fasting insulin levels or insulin resistance (HOMA-IR), the increase in GLP-1 levels in the intervention group suggests that F-BioticTM may positively influence insulin sensitivity through this pathway." (PMID 39835082, 2024). "First, we could not evaluate blood insulin levels and insulin resistance." (PMID 39285495, 2024). "Similarly to our results, in a study of children with obesity, apelin-12 concentrations correlated positively with indices of glucose homeostasis, such as glucose, insulin and HOMA-IR, indicating that apelin overexpression might have a protective role against insulin resistance." (PMID 39519480, 2024). "However, we also cannot rule out psychological stress, which could also favour an insulin resistance state, therefore necessitating higher insulin dose requirements." (PMID 38651404, 2024). "In addition, the importance of HOMA-IR lies in its ability to provide a quick and immediate estimate of insulin secretion and insulin resistance without resorting to investigative procedures like the OGTT, which are not always easily performed in the pediatric age." (PMID 38920551, 2024). "In insulin-resistant human muscle, CHC22 accumulates at sites of GLUT4 over-sequestration, so interference with CHC22 membrane recruitment by targeting either site of the CHC22-p115 interaction defined here could potentially alleviate aberrant CHC22 accumulation during insulin resistance." (PMID 39160272, 2024). "Increased leucine has been hypothesized to lead to insulin resistance through activation of the Target of Rapamycin (TOR) complex 1 pathway, with modulation of beta cell proliferation and insulin secretion and disruption of insulin signaling in skeletal muscle." (PMID 39125441, 2024). "Although, how autocrine insulin signaling contributes to β-cell proliferation under any state remains unclear; multiple transgenic mice studies suggest that IRS2 is critical in β-cell hyperplasia in response to insulin resistance, in addition to regulating β-cell mass." (PMID 38201998, 2024). "However, the H+O diet significantly increased insulin sensitivity in obese mice, evidenced by the results of the insulin tolerance test (IPITT), suggesting olive oil might have advantage in improving insulin resistance." (PMID 38501107, 2024). "Blood insulin levels and insulin resistance could not be evaluated in this study." (PMID 39285495, 2024). "Notably, a substantial increase in fasting insulin and HOMA-IR in 12-month-old mice suggests the onset of insulin resistance during middle age, implying that adipose tissue changes contributing to metabolic dysregulation in old age may commence between young and middle age and worsen with aging." (PMID 38728252, 2024). "Although the causes of insulin resistance are multifactorial, concomitant tissue insulin resistance is neither a prerequisite for our proposed mechanism, nor is it excluded, and the relative role of insulin chain splitting vs cellular insulin resistance is unknown." (PMID 40604313, 2024).
Insulin resistance (continued). "Obesity and insulin resistance are two intimate disorders that negatively affect almost all tissues and systems, suppressing health, eliciting functional alterations in classical and nonclassical insulin-dependent cells, and driving the resurgence of several diseases." (PMID 38991370, 2024). "Furthermore, the sample size was limited and the relative degree of insulin resistance or insulin secretion defects was not likely to be identical in both groups and could not be accurately assessed by a hyperinsulinemic euglycemic insulin clamp." (PMID 39065137, 2024). "Furthermore, it has been suggested that decreased exposure to hepatic insulin lowers the amount of IGF-1 in the blood, which may also lead to an increase in peripheral insulin resistance when combined with a concurrent rise in growth hormone and IGF-binding proteins." (PMID 39768947, 2024). "Furthermore, in these studies, insulin resistance was investigated by HOMA-IR, in contrast to our study which included ISI-M as the primary outcome, which has the advantage of considering kinetic glucose values and has a better correlation with the insulin sensitivity value of peripheral tissue." (PMID 37627476, 2023). "Therefore, this review was conducted to provide a comprehensive overview and summary of the latest in vitro insulin resistance models, particularly 3T3-L1 (preadipocyte), C2C12 (skeletal muscle), and HepG2 (liver) cell lines induced with palmitic acid, high glucose, or chronic exposure to insulin." (PMID 36714242, 2023). "Androgen-treated female-to-male transsexual patients exhibited higher homeostatic model assessment of insulin resistance values than those who did not receive hormonal treatment, indicating that administration of exogenous androgens might increase insulin resistance." (PMID 38068890, 2023). "Insulin tolerance tests were difficult to interpret due to different baseline glucose levels; expressing the data as percentage baseline glucose did not help clarify whether insulin resistance was rescued (data not shown)." (PMID 37712417, 2023). "As insulin resistance in db/db mice is much more extreme than in WTD-fed C57BL/6J mice, it may be interesting to study the effects of colesevelam in mice with a human-like BA composition in the context of a more severe insulin resistant phenotype at the start of the intervention." (PMID 37760936, 2023). "However, rapid catch-up growth and insulin resistance could not fully explain the association between SGA and NAFLD as the present study did not observe any major difference in insulin resistance between children born SGA and AGA." (PMID 36638094, 2023). "Therefore, under conditions of impaired insulin signaling, increased BCAA levels may promote anabolic reactions and prevent some negative consequences of insulin resistance or deficiency." (PMID 36675238, 2023). "Importantly, early changes in metabolic parameters of offspring exposed in utero to BPA include nonfasting hyperinsulinemia as an early marker followed by insulin resistance and/or glucose intolerance as well as islets with decreased insulin content and impaired GSIS ex vivo." (PMID 37134142, 2023). "Insulin resistance cannot explain the complexity of the polycystic ovary syndrome, given that this hypothesis is biased by assuming as a premise that PCOS pathogenesis essentially relies upon defective insulin transduction due to impaired availability of inositolphosphoglycans." (PMID 37047265, 2023). "Given that insulin secretion was not impaired in β cells of multiparous mice at 3 weeks after the last delivery, these data indicate that the insulin secretory function of β cells from multiparous mice deteriorated over time after the last delivery, along with the progression of insulin resistance." (PMID 37903900, 2023).
Insulin resistance (continued). "Importantly, fasting serum insulin levels and Homeostatic Model Assessment for Insulin Resistance (HOMA-IR) did not change significantly in the LDVD group but decreased significantly by 13 ± 8 μIU/mL in the HDVD group as did HOMA-IR, from 2.9 ± 0.2 to 1.8 ± 0.1." (PMID 37189612, 2023). "Therefore, low vitamin D levels may have a negative impact on insulin sensitivity and can contribute to the development of insulin resistance." (PMID 36833019, 2023). "Notably, ammonium levels, insulin sensitivity, and glucose uptake were restored by knocking down or inhibiting MAT2A, suggesting that increased use of methionine might be contributing to insulin resistance." (PMID 36797255, 2023). "To determine whether these hormones participate in the insulin‐sensitizing action of SSTR5 inhibition, we evaluated the effects of alogliptin, a dipeptidyl peptidase 4 (DPP4) inhibitor that increases plasma GLP‐1 and insulin levels, on insulin resistance in KK‐Ay mice." (PMID 36585794, 2023). "Regardless of whether it is defined by insulin resistance, decreased insulin secretion, or a combination of both, the resulting effects extend to other organ systems, intensifying the diversity of clinical manifestations and difficulties related to successful treatment." (PMID 38283440, 2023). "Possible clinical applications of our current finding of a shift in fuel preference from fatty acid to glucose metabolism are not clear; however, non-insulin-dependent pathways to increase glucose uptake and utilization might be beneficial in, e.g., conditions with insulin resistance." (PMID 38001909, 2023). "Furthermore, dapagliflozin improved fasting and 2 h plasma glucose levels, fasting insulin concentrations, and insulin sensitivity as measured by homeostasis-model-assessment-estimated insulin resistance (HOMA-IR), none of these effects being observed in the omega 3 or placebo groups." (PMID 37374340, 2023). "In this metabolic phenotype 1 context, an infrequent one-time bolus insulin secretion does not inhibit gluconeogenesis and glycogenolysis; this may incorrectly be interpreted as hepatic insulin resistance, as is the case for hyperinsulinaemic T2DM (stage-3 metabolic phenotype 3) individuals." (PMID 37958602, 2023). "Furthermore, mice deficient in skeletal muscle β‐catenin did not become more insulin resistant following short‐term HFD, suggesting β‐catenin dysregulation may play a role in the development of insulin resistance." (PMID 36807886, 2023). "Furthermore, one study reported that co-administration of NAC and metformin for 12 months in patients with nonalcoholic steatohepatitis (NASH) decreased serum FBS, fasting insulin and insulin resistance, HDL-C, and TG levels but did not change serum concentrations of TC." (PMID 37794966, 2023). "However, over time, some SCI patients experience insulin resistance attributed to increased adiposity, and consequently, some cells may fail to respond to insulin and glucose is not metabolized as quickly." (PMID 37233646, 2023). "However, MAFLD patients with HUA had much higher fasting insulin, OGIRT AUC, VAT, SAT, Adipo-IR, trunk fat mass, and android fat mass than those with normal SUA, indicating that MAFLD patients with HUA are characterized by more central fat and insulin resistance." (PMID 37749567, 2023). "However, it is important to note that the Homeostatic Model Assessment for Insulin Resistance (HOMA-IR) could not be included in our analysis because the UKBB cohort lacked the fasting insulin and fasting glucose data, which are required for its calculation." (PMID 38434247, 2023). "The analysis of Reactome, KEGG and GO showed that miRNAs down-regulated in the stable CAD patients compared to the control individuals could regulate insulin resistance, insulin signalling, sphingolipid signalling and non-alcoholic fatty liver disease (NAFLD) pathways." (PMID 36717592, 2023).